AWAT2 (acyl-CoA wax alcohol acyltransferase 2)
Description:
Acyltransferase that catalyzes the formation of ester bonds between fatty alcohols and fatty acyl-CoAs to form wax monoesters. Shows a preference for medium chain acyl-CoAs from C12 to C16 in length and fatty alcohols shorter than C20, as the acyl donors and acceptors, respectively. Also possesses acyl-CoA retinol acyltransferase (ARAT) activity that preferentially esterifies 11-cis-retinol, a chromophore precursor of bleached opsin pigments in cone cells. Shows higher catalytic efficiency toward 11-cis-retinol versus 9-cis-retinol, 13-cis-retinol, and all-trans-retinol substrates.
Synonyms: ARAT; DC4; DGAT2L4; MFAT; WS
Tractability: Antibody: UniProt predicts a signal peptide or a membrane-spanning region.
Target class: Enzyme; Transferase
Gene: Protein-coding gene on chromosome X (70,040,542 to 70,049,988, reverse strand). Ensembl gene ENSG00000147160.
Subcellular location: Endoplasmic reticulum membrane
Pathways (Reactome):
Metabolism: Acyl chain remodeling of DAG and TAG; Wax biosynthesis
Sensory Perception: The retinoid cycle in cones (daylight vision)
Gene Ontology:
Molecular function: long-chain-alcohol O-fatty-acyltransferase activity; retinol O-fatty-acyltransferase activity; 2-acylglycerol O-acyltransferase activity; acyltransferase activity, transferring groups other than amino-acyl groups; diacylglycerol O-acyltransferase activity
Biological process: monoacylglycerol biosynthetic process; acylglycerol acyl-chain remodeling; retinoid metabolic process; wax biosynthetic process; retinol metabolic process
Cellular component: endoplasmic reticulum membrane
Homologues: Orthologues: chimpanzee AWAT2 (99% identical), macaque AWAT2 (91% identical), dog AWAT2 (84% identical), mouse Awat2 (84% identical), rabbit AWAT2 (83% identical), rat Awat2 (81% identical), pig AWAT2 (77% identical), guinea pig AWAT2 (76% identical), Caenorhabditis elegans dgtr-1 (36% identical), Caenorhabditis elegans K07B1.4 (35% identical), Caenorhabditis elegans dgat-2 (35% identical), Caenorhabditis elegans Y53G8B.2 (34% identical), and 3 more. Paralogues in human: DGAT2L6 (51% identical), AWAT1 (50% identical), DGAT2 (48% identical), MOGAT2 (42% identical), MOGAT3 (40% identical), MOGAT1 (39% identical).
Diseases named in the same sentence as AWAT2 in open-access papers:
AWAT2 is named in the same sentence as 11 diseases in open-access papers, as found by Europe PMC text mining. Sharing a sentence is not in itself a finding about the gene and the disease. The quoted sentences say what the papers report.
dry eye (3 papers, 2021 to 2025). "Previously, changes in MG lipidomes induced by inactivation of critical genes of meibogenesis, such as Elovl3, Soat1, Awat2, Sdr16c5/Sdr16c6, and others were shown to cause MG dysfunction (MGD) and dry eye in experimental animals." (PMID 41373590, 2025). "Recently, it was reported that Awat2 KO mice exhibit a dry eye phenotype accompanied by obstruction of the meibomian gland orifice." (PMID 34113821, 2021). "In the present study, we have elucidated the detailed composition of several ester-bond-containing meibum lipids in mice and gained insights into their roles in dry eye prevention and the contributions of Awat1 and Awat2 to their production." (PMID 34113821, 2021). "Here, we created single and double knockout (KO and DKO, respectively) mice for the two acyl-CoA wax alcohol acyltransferases (Awat1 and Awat2) and investigated their dry eye phenotypes and meibum lipid composition." (PMID 34113821, 2021). "Recently, during the preparation of this manuscript, a paper investigating the dry eye phenotypes of Awat2 KO mice was published." (PMID 34113821, 2021). "We then examined other dry eye phenotypes, such as corneal damage and corneal irregularity, in Awat2 KO mice." (PMID 34113821, 2021). "Here, we performed time-dependent analyses of dry eye phenotypes on Awat2 KO mice using a relatively large number of samples (n = 10)." (PMID 34113821, 2021). "The dry eye phenotypes, in descending order of severity, in all four mouse lines are as follows: Awat2 KO mice ≈ DKO mice > Tg Cyp4f39 KO mice > Awat1 KO mice." (PMID 34113821, 2021). "Thus, the Awat2 KO mice exhibited a time-dependent progression of dry eye." (PMID 34113821, 2021). "Awat2 knockout mice and Awat1 and Awat2 double knockout mice expressed severe dry eye with MGD, whereas Awat1 knockout mice had only mild dry eye." (PMID 35685417, 2022). "Awat2 KO and DKO mice exhibited severe dry eye with meibomian gland dysfunction, whereas Awat1 KO mice had mild dry eye." (PMID 34113821, 2021). "The Awat2 KO and DKO mice showed severe MGD dry eye phenotypes, indicating that WEs and some WdiEs in the meibum lipids are important for TFLL function." (PMID 34113821, 2021). "In the present study, we generated Awat1 KO, Awat2 KO, and Awat1 Awat2 double KO (DKO) mice and used them to examine the contribution of Awat1 and Awat2 to the production of meibum lipids, as well as their roles in dry eye prevention." (PMID 34113821, 2021).
hypohidrotic ectodermal dysplasia (1 paper, 2021). A genetic disorder of ectoderm development characterized by malformation of ectodermal structures such as skin, hair, teeth and sweat glands. "This represents the first form of X-linked hypohidrotic ectodermal dysplasia in cattle that affected both EDA and AWAT2 genes." (PMID 33801223, 2021).
AWAT2 also shares sentences with these, for which no sentence is quoted: malaria (4 papers); tumor (4); cancer (2); cerebral malaria (2); Atrophy (1); hair diseases (1); melanoma (1); thyroid cancer (1); thyroid nodule (1).